CPS1 (carbamoyl-phosphate synthase 1)
Diseases named in the same sentence as CPS1 in open-access papers (continued):
Sharing a sentence is not in itself a finding about the gene and the disease.
non-small cell lung carcinoma (12 papers, 2004 to 2025). A group of at least three distinct histological types of lung cancer, including non-small cell squamous cell carcinoma, adenocarcinoma, and large cell carcinoma. "A previous study demonstrates that AMPK downregulates carbamoyl phosphate synthase 1 (CPS1) in Kras-mutated non-small-cell lung cancer (NSCLC) cells." (PMID 33917483, 2021). "AT067-H09 and H3B-120 are two inhibitors of CPS1 in vitro, in cultured hepatocytes and in cultured non-small cell lung carcinoma cell lines that appear to be promising antitumor drug candidates." (PMID 37047726, 2023). "The NAGS protein is expressed in two cell lines commonly used to model non-small cell lung carcinoma; this provides a molecular mechanism for CPS1 activity and increased production of CP in the two cell lines." (PMID 37047726, 2023). "Recently, it was found that CPS1 expression correlates inversely with liver kinase B1 (LKB1) activation in non-small-cell lung cancer (NSCLC)." (PMID 29895729, 2018). "Furthermore, context-dependent function is also identified in case of Kirsten rat sarcoma viral oncogene homolog (KRAS)/LKB1 mutant non-small cell lung cancers where overexpression of CPS1 drove de novo pyrimidine biosynthesis pathway dependency." (PMID 40961924, 2025). "However, CPS1 is overexpressed in a subset of non-small cell lung cancer (NSCLC), colon cancer, glioblastoma and cholangiocarcinoma, in which it is associated with poor prognosis." (PMID 33917483, 2021). "Although these studies provided evidence of CPS1 enzymatic activity in tumor cells, only one study showed the presence of NAGS in cell lines that model non-small cell lung carcinoma and express CPS1." (PMID 37047726, 2023). "The UC enzyme, carbamoyl-phosphate synthase 1 (CPS1), maintains the pyrimidine pool in non-small cell lung cancer by activating CAD, and silencing CPS1 in KL cells induces cell death and inhibits tumor growth in vivo due to the depletion of pyrimidines." (PMID 36338624, 2022).
colorectal cancer (8 papers, 2016 to 2024). A primary or metastatic malignant neoplasm that affects the colon or rectum. "A potent study showed the overexpression of CPS1 has been linked to both unfavorable therapeutic responses in colorectal cancer patients receiving neoadjuvant concurrent chemoradiotherapy, according to new research (CCRT)." (PMID 36139498, 2022). "CPS1 expression has been associated with the initiation and progression of colorectal cancer." (PMID 30967136, 2019). "CPS1 has also been identified as a biomarker of progression in colorectal cancer." (PMID 35557945, 2022).
colon cancer (7 papers, 2004 to 2024). "Our findings also concur with previous research showing Cps1 is associated with apoptosis in colorectal tumors and later-stage colon cancer tissues possessing decreased Cps1 expression levels." (PMID 38730628, 2024). "The CPS1 expression of normal colon cell line NCM460 is higher than the colon cancer cell lines HCT116 and HCT8, consistent with the tissue level data." (PMID 33869206, 2021). "Recently, it has been reported that CPS1 is overexpressed in approximately 43% of human colon cancer, suggesting a role for Hep par 1 in the progression of colorectal adenocacinoma." (PMID 27956971, 2009). "The overexpression of CPS1 is related to a poor prognosis in colon cancer." (PMID 33915902, 2021). "However, upregulation of the carbamoyl phosphate synthase 1 (CPS1) has been found to increase CP production in NSCLC, HCC, and colon cancer." (PMID 38216787, 2024).
glioblastoma (7 papers, 2013 to 2024). The most malignant astrocytic tumor (WHO grade IV). "Previous studies have demonstrated that CPS1 expression is upregulated in glioblastoma multiforme and that overexpression of CPS1 is associated with poor therapeutic response and adverse outcomes among rectal cancer patients receiving concurrent chemoradiotherapy." (PMID 34604089, 2021). "Conversely, up-regulation of the CPS1 gene and overexpression of CPS1 protein are described in glioblastoma and carcinomas of the urinary bladder, ovary, lung and colon." (PMID 37443694, 2023). "Overexpression of CPS1 is found in glioblastoma, ovarian carcinoma, urothelial carcinoma of the urinary bladder, lung adenocarcinoma, breast cancer and colorectal cancer." (PMID 37443694, 2023). "Median expression of NAGS, CPS1, and citrin mRNA was higher in glioblastoma multiforme (GBM), glioma, and stomach adenocarcinoma (STAD) samples compared to the matched normal tissue." (PMID 37047726, 2023). "Aberrant overexpression of NAGS could contribute to poor outcomes for patients with glioblastoma and glioblastoma multiforme independently of CPS1." (PMID 37047726, 2023). "The median NAGS, CPS1, and citrin expression was between 1.4- and 4-fold higher in glioblastoma multiforme (GBM, n = 166), glioma (GBMLGG, n = 696), stomach adenocarcinoma (STAD, n = 415), and stomach and esophageal carcinoma (STES, n = 600)." (PMID 37047726, 2023). "Therefore, we hypothesize that CPS1 and citrin promoters could function in the glioblastoma, glioblastoma multiforme, stomach adenocarcinoma, and stomach and esophagus carcinoma cells." (PMID 37047726, 2023). "This hypothesis could be tested with expression constructs in which NAGS, CPS1, or citrin promoters and enhancers control reporter gene expression in cell lines that model glioblastoma, glioblastoma multiforme, stomach adenocarcinoma, and stomach and esophagus carcinoma." (PMID 37047726, 2023). "The correlation between NAGS, CPS1, and citrin mRNA expression in the individual glioblastoma, GBM, LUAD, and STAD samples was very weak." (PMID 37047726, 2023). "The remaining glioblastoma multiforme samples exhibited either shallow deletions or gains of the NAGS and CPS1 genes, and either gains or amplifications of the citrin gene." (PMID 37047726, 2023). "NAGS and CPS1 loci were diploid in the 82 and 89%, respectively, of glioblastoma samples while 5–10% of glioblastoma samples exhibited either shallow deletions or gains of NAGS and CPS1 genes." (PMID 37047726, 2023). "The majority of glioblastoma multiforme samples were diploid for NAGS and CPS1 loci and exhibited gains of the citrin gene." (PMID 37047726, 2023). "On the other hand, alterations of SGCG, HTR4, ITGB1, CPS1, PROS1 and INPP5A were detected predominantly in anaplastic astrocytoma, while alterations of PDE4D were present in both glioblastoma subtypes." (PMID 24358143, 2013). "Glioblastoma and glioblastoma multiforme had similar patterns of NAGS, CPS1, and citrin CNV." (PMID 37047726, 2023). "In our set of samples alterations of CPS1 were mainly found in grade III anaplastic astrocytoma with low level of genomic instability, suggesting potential role of this enzyme in neoplastic progression of secondary glioblastoma." (PMID 24358143, 2013).
liver cancer (7 papers, 2020 to 2024). An epithelial or non-epithelial malignant neoplasm that arises from the liver. "Four weeks later, we were pleasantly surprised to find that CPS1‐AAV had the ability to inhibit liver cancer progression and distant lung metastasis." (PMID 39387452, 2024). "In NSCLC and intrahepatic cholangiocarcinoma of the liver cancer, the mitochondrial urea cycle enzyme CPS1 was downregulated either directly or via reduced expression of NAGS, the enzyme that produces its essential cofactor N-acetylglutamate, respectively." (PMID 35838048, 2022). "Specific knockout of liver NFIB leads to increased expression of ASS1 and CPS1, which promotes the occurrence of liver cancer by affecting the urea cycle." (PMID 35655758, 2022). "Based on CPS1's anti‐tumor effect, we hope it can improve the efficacy of liver cancer drugs." (PMID 39387452, 2024). "The interacting protein carbamyl phosphate synthetase 1 (CPS1) has been shown to be downregulated in both HCC and AFB1 exposure, highlighting the importance of studying the mechanisms underlying UBC upregulation in liver cancer and its interaction with CPS1." (PMID 38201191, 2024). "Therefore, the mechanism of ASS1 and CPS1 in liver cancer is still unclear, and further studies are needed." (PMID 35655758, 2022). "Moreover, urea cycle enzymes (ASS1 and CPS1) are inhibited in liver cancer, so the expression of them have decreased in liver cancer cells, and the increase of ASS1 and CPS1 caused by knocking down NFIB becomes insignificant." (PMID 35655758, 2022). "CPS1 is a mitochondrial protein and a prognostic marker of liver cancer." (PMID 33783990, 2021). "Thus, the highly expressed and acetylated CPS1 in liver cells may be involved in development of liver cancer." (PMID 33783990, 2021). "Through clinical pathological analysis, we revealed that negative CPS1 expression was significantly correlated with tumor size, macrovascular invasion, Bacelona Clinic Liver Cancer (BCLC) stage and poor differentiation." (PMID 39387452, 2024). "CPS1, regulated by MAP kinase, exhibits increased activities in liver cancer." (PMID 32850805, 2020). "In addition, CPS1 has three different expression patterns in liver cancer (negative expression, low expression, and high expression)." (PMID 39387452, 2024).
Obesity (6 papers, 2015 to 2025). Accumulation of substantial excess body fat. "Further, age, obesity (BMI > 30 kg/m2), diabetes mellitus and ALT werefound to be risk factors whereas A-allele from CPS1 was a protective factor from liver fibrosis." (PMID 35232986, 2022). "This implies that CPS1 may serve as a crucial target for Cpn against obesity." (PMID 40438591, 2025).
acute liver failure (5 papers, 2018 to 2025). Rapid deterioration of liver function causing encephalopathy and coagulopathy. "Similar to mtDNA, GLDH and nuclear DNA fragments, CPS1 appears to be a general biomarker of cell death involving mitochondria, which means that it is detectable in acute liver failure patients with different etiology." (PMID 30873497, 2018). "Moreover, circulating CPS1 is a marker of acute liver failure in patients with acetaminophen-induced injury with a half-life in mice sera of ∼126 min." (PMID 38013089, 2023). "It was suggested that serum exosome-derived CPS1 levels might serve as viable biomarkers for accurately diagnosing and predicting the onset of acute liver failure, as well as its fatality rates." (PMID 37408250, 2023). "Conversely, CPS1 levels are elevated in the plasma of NAFLD patients with varying fibrosis extents and in the serum of individuals experiencing acetaminophen-induced acute liver failure, with levels diminishing post-injury recovery." (PMID 40438591, 2025). "Another hepatic mitochondrial matrix protein, carbamoyl phosphate synthetase-1 (CPS1), was detected during Fas-induced apoptosis and APAP-induced necrosis in cell culture supernatants, in mice in vivo and in plasma of human acute liver failure patients." (PMID 30873497, 2018).
bladder cancer (5 papers, 2014 to 2024). "We further found that the expression of CPS1 was higher in the bladder cancer cell lines UMUC3 and T24 than in the SVHUC1 cell line." (PMID 31565867, 2019). "Survival data from the TCGA database showed that high expression of CPS1 was related to a worse prognosis in patients with bladder cancer." (PMID 31565867, 2019). "We indicated that CARD10 promote bladder cancer growth via CPS1 and maybe a potential therapeutic target in bladder cancer." (PMID 31565867, 2019). "In addition, we found that CARD10 impacted nucleotide metabolism through CPS1 in bladder cancer cells." (PMID 31565867, 2019).
breast carcinoma (5 papers, 2004 to 2021). "In terms of feasibility, in our hands, semiquantitative scoring of CAD and CPS1 immunoreactivity was adapted in analogy to the scoring of hormone receptor and HER2neu expression, which is part of routine histopathological diagnostics of breast cancer." (PMID 33670206, 2021). "One of the mitochondrial proteins, a urea cycle enzyme carbamoyl-phosphate synthetase I (CPS1), is significantly overexpressed in breast cancer-resistant cell lines due to the increase in the number of CPS1 positive breast cancer paclitaxel-resistant cells as found by us." (PMID 35008510, 2021). "Recently, we reported alterations in ABCC3, CPS1, and TRIP6 gene expression in a breast cancer cell line resistant to paclitaxel." (PMID 35008510, 2021). "We further tested the relationship between ErbB-2 expression and the expression of UCHL1, CPS1 and copine III in a panel of breast cancer cell lines." (PMID 14710226, 2004). "In this study, we detected three mitochondrial proteins (CPS1, ATAD3A/ATAD3B, and ABHD11) and one lysosomal protein (cathepsin D) with different expressions in paclitaxel-resistant MCF7/PacR breast cancer cells compared to paclitaxel-sensitive MCF7 breast cancer cells." (PMID 31248089, 2019).
citrullinemia (5 papers, 2018 to 2025). Citrullinemia is an autosomal recessively inherited disorder of urea cycle metabolism and ammonia detoxification characterized by elevated concentrations of serum citrulline and ammonia. "SLEs may be observed in carbamoyl phosphate synthetase I (CPS1) deficiency, ornithine transcarbamylase (OTC) deficiency and citrullinemia." (PMID 36295831, 2022).
coronary artery disease (5 papers, 2016 to 2022). "A recent MR analysis, which aimed to evaluate the causal association between circulating glycine and coronary artery disease, also highlighted the potential pleiotropy of the CPS1 rs1047891 SNP and did not obtain conclusive evidence for causality." (PMID 36307799, 2022).
diabetes (5 papers, 2017 to 2025). "For example, although the plasma glycine concentration is associated with an increased risk of diabetes, no genetic variants that are significantly associated with a risk of diabetes have been identified within the CPS1 locus." (PMID 30659259, 2019). "This discovery suggested that CPS1 may serve as a novel target for therapeutic interventions aimed at modulating gluconeogenesis and addressing metabolic dysregulations associated with conditions such as diabetes." (PMID 39193349, 2024). "The discovery of cynarin as a natural inhibitor of CPS1 suggested its potential as a therapeutic agent for diabetes treatment." (PMID 39193349, 2024).
gastric cancer (5 papers, 2011 to 2025). A primary or metastatic malignant neoplasm involving the stomach. "Several recent studies showed the associations of CPS1 with some cancers such as gastric cancer and ovarian cancer." (PMID 37938151, 2023).
migraine (5 papers, 2021 to 2025). "For instance, the SNP rs1047891, found in the CPS1 gene, is linked to a reduced likelihood of migraine but an increased likelihood of CKD." (PMID 38672983, 2024). "This SNP is located near CPS1, previously reported to associate with migraine in women and eGFR." (PMID 37306871, 2023). "The women-specific (GERA + UKB) meta-analysis (22,500 migraine cases and 279,762 controls) identified 19 loci (P < 5.0 × 10−8), of which three, CPS1 on chromosome 2, PBRM1 on chromosome 3, and SLC25A21 on chromosome 14, were additional novel loci." (PMID 34294844, 2021). "This may suggest a nonenzymatic function of CPS1 as an anti-inflammatory cytokine and provides a mechanism for its protective action, possibly reducing systemic inflammation and oxidative stress, which could protect against neurogenic inflammation associated with migraines during CKD." (PMID 38672983, 2024). "Current progresses from genomic and proteomic studies have highlighted common pathogenic mechanisms underlying migraine and CKD involving vascular development and endothelial function, and loci mapping to genes CPS1 and SMG6 are found to affect both migraine and kidney function." (PMID 37306871, 2023). "Among the sex-specific loci associated with migraine susceptibility in women but not in men, less is known about the role of the identified CPS1 and SLC25A21 in regard to the biologic pathways underlying migraine." (PMID 34294844, 2021). "CPS1 rs1047891, PBRM1 rs11718509, and SLC25A21 rs10150336 were significantly associated with migraine in women (P < 5.0 × 10−8) but not in men (P > 0.05)." (PMID 34294844, 2021).
steatosis (5 papers, 2015 to 2025). Increased lipid within the cytoplasm of cells. "CPS1-deficient hepatocytes can cause steatosis and glycogenosis." (PMID 26418247, 2015). "CPS1 expression by RNA-seq was found to be diminished in both bland steatosis (0.81 fold; FDR: 0.156) and NASH-fibrosis (0.78 fold; FDR: 0.052) when compared to healthy controls, but only reached statistical significance in the latter." (PMID 35232986, 2022). "Nevertheless, CPS1 protein was found to be increased in steatosis simple patients, probably as a compensatory mechanism to restore hepatic homeostasis during the first stages of liver injury." (PMID 35232986, 2022). "Previous proteomic studies on non-alcoholic fatty liver showed that serum concentration of CPS1 decreases gradually in the order of control steatosis and NASH patient subjects and CPS1 has been confirmed to be serum candidate markers of NAFLD." (PMID 32586350, 2020). "Interestingly, steatosis in primary hepatic cells was also associated with OTC and CPS1 promoter hypermethylation, decreased OTC and CPS1 gene expression, and ammonia generation." (PMID 33490737, 2021). "Carbamoyl phosphate synthase 1 (CPS1) and 78 kDa glucose-regulated protein (GRP78) were the two differentially expressed proteins, and they decreased from control to steatosis and NASH patients, representing potential candidate biomarkers." (PMID 40004054, 2025). "The qualitative scale showed that 60% (3/5) of patients with NASH-fibrosis were low positive for CPS1 and none of the simple steatosis patients were found to be low positive (p = 0.01)." (PMID 35232986, 2022).
Cirrhosis (4 papers, 2019 to 2025). A chronic disorder of the liver in which liver tissue becomes scarred and is partially replaced by regenerative nodules and fibrotic tissue resulting in loss of liver function. "Adhering to the recommended protein intake may help cirrhosis patients and CPS1 heterozygotes avoid high blood and brain ammonia levels and any associated cognitive dysfunction." (PMID 31366360, 2019).
Coma (4 papers, 2017 to 2024). The complete absence of wakefulness and consciousness, which is evident through a lack of response to any form of external stimuli. "Collectively, our data suggested a promising therapeutic approach targeting CPS1 as a potential intervention for type 2 diabetes." (PMID 39193349, 2024).
fibrosis (4 papers, 2021 to 2025). the formation of excess fibrous connective tissue in an organ or tissue in a reparative or reactive process. "Further, 64.2% (113/175) of patients bearing A-allele from CPS1 variant did not display hepatic fibrosis in liver biopsy vs. 53.4% (110/207) of patients without A-allele and without fibrosis (p = 0.03)." (PMID 35232986, 2022). "A significant downregulation in mRNA was observed in CPS1 and ornithine transcarbamylase (OTC1) in simple steatosis and NASH-fibrosis patients versus controls." (PMID 35232986, 2022). "We found the expression of OTC, CPS1, ASS1, and ASL was highly upregulated in BLM-induced fibrosis, and these enzymes were also downregulated after treatment with TL." (PMID 33995084, 2021).
intrahepatic cholangiocarcinoma (4 papers, 2022 to 2025). A carcinoma that arises from the intrahepatic bile duct epithelium in any site of the intrahepatic biliary tree. "CRhi intrahepatic cholangiocarcinoma tumors were also enriched for purines compared with pyrimidines, consistent with their downregulated CPS1 activity that reduced the supply of carbamoyl phosphate to de novo pyrimidine synthesis and enhanced aspartate availability for de novo purine synthesis." (PMID 35838048, 2022).